IL6 (interleukin 6)
Diseases named in the same sentence as IL6 in open-access papers (continued):
Sharing a sentence is not in itself a finding about the gene and the disease.
tuberculosis (continued). "However, we found marginally significant associations between higher baseline IL-6 concentrations and unfavorable tuberculosis treatment outcomes when restricted to HIV coinfected participants (Table-3)." (PMID 34711538, 2022). "This study explored an immunological detection method for tuberculosis infection cells based on HupB protein-induced IL-6 release test, which can be used to enhance the diagnosis diagnostic accuracy of TB." (PMID 37077246, 2023). "However, few studies have reported an association between IL-6 and tuberculosis treatment outcomes." (PMID 34711538, 2022). "Previously, rs1800796 (−572 C/G) of IL-6 was detected to be associated with adult TB and the regulatory effects of this SNP on IL-6 production in plasma and CD14+ monocyte cultures stimulated with a M. tuberculosis product were also conformed." (PMID 24772425, 2014). "Overexpression of mir3179 has been implicated along with slightly altered TNF and IL-6 levels in Tuberculosis (TB) group compared to controls." (PMID 24587348, 2014). "Neither Staphylococcal Enterotoxin B-mediated T-cell stimulation nor phytohemagglutinin or Pam3CSK4 induced monocyte cytokines (i.e., Interleukin-6, Interleukin-8, Tumour Necrosis Factor-α) were affected by the tuberculosis patients' serum samples." (PMID 41795482, 2026). "Tuberculosis triggers a robust immune response that involves the release of key pro-inflammatory cytokines, including tumor necrosis factor-alpha, interleukin-1, interleukin-6 (IL-6), interferon-gamma (IFN-γ), and interleukin-12 (IL-12)." (PMID 39941433, 2025). "Elevated IL-6 and G-CSF responses correlate with active tuberculosis, suggesting potential utility in distinguishing latent from active disease." (PMID 41488476, 2025). "Previous studies have reported a significant increase in the serum levels of the inflammatory factor IL-6 in tuberculosis patients." (PMID 40370406, 2025). "On the other hand, IL-1β and IL-6 participate in the formation of tuberculosis granulomas, regulate the activation of macrophages and T-lymphocytes, and influence the secretion of interferon-γ and other key cytokines." (PMID 40141021, 2025). "Although IL-6 is widely expressed during infections, in our study of patients with confirmed tuberculosis, we found that it assists in distinguishing the severity of the disease." (PMID 40164948, 2025). "IL-6, as a marker for severe tuberculosis patients, suggests that studying the formation and mechanisms of action of IL-6 is of significant importance for the prevention and treatment of tuberculosis." (PMID 40164948, 2025). "The key cytokines and chemokines that play a role in the comorbidity of COPD and tuberculosis are interleukins 1β, 6, and 8 (IL-1β, IL-6, IL-8), TNF-α, and interferon gamma (IFN-γ)." (PMID 40141021, 2025). "utilized machine learning techniques and found that among HIV-positive patients, those with tuberculosis exhibited significantly elevated levels of inflammatory markers including IL-2, IL-4, IL-6, IL-10, TNF-α, and IFN-γ." (PMID 41322408, 2025). "Cytokine blood levels of interferon γ, IL-6 and IL-1 are used as markers for infectious diseases such as tuberculosis, while IL-1 and IL-6 are considered to characterize patients with inflammatory disorders, rheumatoid disease and cancer." (PMID 37298597, 2023). "Six of seven cytokines were significantly higher in tuberculosis patients as compared to contacts and four of these (i.e., IL-6, IP-10, IL-10, and IL-22) were detectable in the majority of tuberculosis patients." (PMID 35759173, 2023). "This suggested direct effects of high IL-6 plasma concentrations on T-cell responses of tuberculosis patients." (PMID 36650358, 2023). "In this study, we analyzed the concentrations of selected plasma cytokines (i.e., IL-6, IP-10, IL-10, IL-22, IFNγ, GM-CSF, IL-8) and M. tuberculosis sputum burden in patients with tuberculosis (n = 76)." (PMID 35759173, 2023).
tuberculosis (continued). "IL-6 showed the strongest discriminating capacity for tuberculosis disease and in combination with IL-10 concentrations efficiently classified paucibacillary tuberculosis cases as well as those with fatal disease outcome." (PMID 35759173, 2023). "Previously, we demonstrated that aberrant high serum IL-6 and IL-10 concentrations affected T-cell functions in tuberculosis patients." (PMID 35759173, 2023). "In this sense, high IL-6 levels have been found to correlate with delayed wound healing in tuberculosis patients." (PMID 37047181, 2023). "Combinations of different plasma cytokine (namely, IL-6, IL-10, and IP-10) efficiently classified tuberculosis patients with differential mycobacterial burden and especially IL-6 qualified as a biomarker candidate for early treatment response." (PMID 35759173, 2023). "IL-6 and IP-10 correlated in tuberculosis patients prior to treatment (r = 0.4, p = 0.011) and at week 6 (r = 0.34, p = 0.030)." (PMID 35759173, 2023). "Recently, we described aberrant high plasma levels of specific cytokines (i.e., IL-6, IP-10, IL-10, IL-22) in tuberculosis patients." (PMID 36650358, 2023). "Other candidates, like IL-6, have been shown to have an even higher sensitivity to detect T-cell responses in tuberculosis patients including paucibacillary cases." (PMID 36650358, 2023). "Stimulation of Mtb-HSP PBMCs resulted in an increase in the level of pro-inflammatory cytokines, TNF-α and IL-6, in the sera of patients with SA and tuberculosis compared to those of healthy controls." (PMID 36982159, 2023). "Th2 cytokines, i.e., IL-4, IL-6, IL-10, IL-13, etc., inhibit Th1 responses and thus cross-regulate and influence the progression to active tuberculosis." (PMID 36776550, 2022). "It has been shown that IL-12 can be used as an adjuvant to improve the effect of tuberculosis treatment IL-6 has been reported to induce B cells to differentiate into and enhance CD8+ T cells differentiation." (PMID 36451816, 2022). "IL-6 is involved in inflammation and pathology and is thus believed to play a role in disease progression in tuberculosis." (PMID 36671761, 2022). "This study showed that IL-6 plays a major role in the priming a Th1 response to a tuberculosis vaccine." (PMID 35679246, 2022). "TNF-a and IL-6 levels in serum or peripheral blood mononuclear cells (PBMCs) were shown to be significantly higher in active tuberculosis compared to healthy controls." (PMID 35457250, 2022). "IL-6 and IP-10 have considerable potential to diagnose tuberculosis, and biologic companies already exist to develop related products." (PMID 35345666, 2022). "A study showed that all MMP-8, MMP-9, TIMP-1, IL-6, VEGF, and TGF-b1 are higher in exudates compared to transudates and that MMP-8 and IL-6 are significantly higher in tuberculosis patients than in cancer patients." (PMID 35326567, 2022). "The finding that the level of IL-10, a cytokine with immune regulatory functions, correlates with IL-6 expression and serum levels in tuberculosis is seemingly controversial." (PMID 34035497, 2021). "In line with our data, the overexpression of Hsp70 significantly prevented TNF-α and IL-6 release and mRNA expression in rat macrophages and tuberculosis patient’s macrophages." (PMID 32899721, 2020). "The role of IL6 in anti-tuberculosis immunity is less well-defined, but a number of studies suggest a role for IL6 in Mtb control." (PMID 31736945, 2019). "One of these studies was an outpatient cohort study that followed participants with HIV-associated tuberculosis and showed that higher pre-ART levels of MCP-1/CCL2, eotaxin, IL-10, TNF-α, and IL-6 were associated with 6-month mortality." (PMID 31276515, 2019). "Through the literature search, we found that interleukin gene is related to the occurrence of tuberculosis, few studies have explored the association between IL4, IL6, and IL10 polymorphisms and PTB risk in Chinese populations." (PMID 29662655, 2018).
tuberculosis (continued). "IL-6 is a biomarker for tuberculosis, as increased levels are observed in patients with tuberculosis that is required for a T cell response against M. tuberculosis infection." (PMID 29867915, 2018). "IL-6, although important for control of tuberculosis in mice model, in humans is considered as a correlate of disease progression because of its role in inflammation and pathology." (PMID 28261567, 2017). "Since increased IL-6 plasma levels were described in tuberculosis previously, we measured plasma IL-6 levels and detected increased IL-6 concentrations in tuberculosis patients as compared to healthy contacts (p < 0.001)." (PMID 28582466, 2017). "Higher IL-6 plasma concentrations were described for tuberculosis, and we confirmed higher IL-6 plasma concentrations in a subgroup of tuberculosis patients in the present study." (PMID 28582466, 2017). "The importance of cytokine IL-6 have been shown studies murine models of mycobacterial infections as well in vaccination with a tuberculosis subunit vaccine demonstrating that IL-6 is needed for optimal T-cell development." (PMID 26840977, 2016). "In experimental tuberculosis, NOD knockout mice were similarly susceptible to M. tuberculosis infection while NOD-deficient DCs produced less IL-12 as well as IL-6 and IL-10 upon stimulation with mycolylarabinogalactan peptidoglycan." (PMID 23805193, 2013). "Within tuberculosis patients the BMI and leptin levels were positively correlated and decreased with increasing disease severity, whereas higher concentrations of IL-6, CRP, IL-1β, cortisol, and ghrelin were seen in cases with moderate to severe tuberculosis." (PMID 22022605, 2011). "Elevated IL-6 levels in tuberculosis are correlated with the active period of the disease and may reflect the degree of bacterial load." (PMID 40141021, 2025). "Moreover, a similar correlation was observed in samples from patients suffering from spinal tuberculosis, suggesting IL-6 plays a key mediatory role in the lncRNA-NEAT1-mediated immune response in tuberculosis." (PMID 39770858, 2024). "IL-6, IP-10, IL-10, and IL-22 were detectable in the majority of tuberculosis patients (> 50%), whereas IFNγ and GM-CSF were measurable only in minor subsets of both study groups (IFNγ: 41.1% in patients, 25.0% in contacts; GM-CSF: 21.4% in patients, 2.5% in contacts)." (PMID 35759173, 2023). "Hence, IL-6 qualifies as a candidate marker for treatment efficacy and recovery in tuberculosis patients." (PMID 35759173, 2023). "Therefore, we predicted central DEGs in the PPI network and noted strong interactions between TNF, IL-6, IL-10, IL-1β, CSF-2, IL-4, CXCL8, IFN-γ, IL-1α, and CXCL1, all of which are strongly associated with tuberculosis." (PMID 37818041, 2023). "Due to the different structure and epitopes of hupB and other antigens (HTDY and LAM) such as E6C10, when HupB protein re-stimulates PBMC of tuberculosis patients in vitro, more memory immune cells producing IL-6 will be activated, prolifitated and produce IL-6." (PMID 37077246, 2023). "According to the specific induction of IL-6 by PBMC of Mycobacterium tuberculosis HupB in patients with tuberculosis, in order to compare the detection effect of two antigens on patients with negative and positive bacteria, and analyze the application value of combined diagnosis." (PMID 37077246, 2023). "IL-6 plasma concentration may also be a marker of disease severity since we detected lower IL-6 levels in tuberculosis patients with low M. tuberculosis sputum burden (TB-Pb)." (PMID 35759173, 2023). "HupB can specifically stimulate PBMCs from tuberculosis patients to release IL-6." (PMID 37077246, 2023). "In both tuberculosis and carciogenesis, Il-6 play an important role again." (PMID 37563331, 2023).
tuberculosis (continued). "In the current study, we scanned the secreted cytokine spectrum of HupB-stimulated PBMCs from PTB patients, and found that IL-6 was the only boosted inflammatory factor, suggesting HupB-induced IL-6 releasing may be an immune marker of active tuberculosis." (PMID 37077246, 2023). "In addition, it was confirmed that metformin increased proinflammatory cytokines (TNF-α, IL-1α, IL-1β, IL-6, IL-18, IL-8, and IFN-α) in Mycobacterium tuberculosis (causative agent of tuberculosis)-infected macrophages." (PMID 37700364, 2023). "In conclusion, we observed that a combination of IL-6, IL-10 and IP-10 could potentially differentiate between tuberculosis patients with different mycobacterial burden." (PMID 35759173, 2023). "Higher IL-6 levels discriminated efficiently between tuberculosis patients and contacts." (PMID 35759173, 2023). "Furthermore, IL-6 was identified as a marker of early treatment response in tuberculosis patients and holds promise for treatment monitoring." (PMID 35759173, 2023). "Pre-treatment IL-6 is a biomarker for unfavorable tuberculosis treatment outcomes." (PMID 34711538, 2022). "Our data support the role of IL-6 as a biomarker for unfavorable tuberculosis treatment outcomes." (PMID 34711538, 2022). "IL-6 is secreted by Toll-like receptor 2-expressing cells in response to the presence of Mycobacterium tuberculosis early in infection and is involved in anti-tuberculosis immunity in the body." (PMID 29662655, 2018). "In S. pneumoniae stimulations, percentages of IL-6+ and TNF-α+ monocyte counts (q = 0.003) and IL-6+ absolute monocyte (q = 0.003) counts were lower in HIV-tuberculosis patients, as were percentages and absolute counts of IL-6+ (q = 0.003) and TNF-α+ (q = 0.01) neutrophils." (PMID 28369200, 2017). "The distribution of IL-6 plasma concentrations indicated two subgroups of tuberculosis patients." (PMID 28582466, 2017). "Some investigators have suggested that high IL-6 levels are associated with non-cavitary tuberculosis and can be regarded as a potent biomarker of M. tuberculosis infection." (PMID 26881918, 2016). "Patients with tuberculosis disease also have a significant elevation in IL-1, IL-2, IL-6 and IL-22." (PMID 26835156, 2015). "Additionally, C1qC protein level in pleural effusion shows improved power in discriminating tuberculosis from non-tuberculosis pleurisy when compared to other inflammatory markers, such as IL-6 and TNF-α." (PMID 24647646, 2014). "IL-6 has been reported to participate in the immunopathogenesis of tuberculosis." (PMID 23028695, 2012). "For example, studies in IL-6 gene-disrupted mice suggest a role in protection against tuberculosis." (PMID 22304898, 2012). "IL-6, a pleiotropic inflammatory cytokine expressed by a wide range of immune cells including macrophages in response to mycobacterial infection, has been proposed to play an important role in protection against tuberculosis." (PMID 22384131, 2012). "Furthermore, IL-6 plays a crucial role in driving T cell responses during tuberculosis, and we found a significant induction of IL-6 mRNA on day 21 post infection." (PMID 21249199, 2011). "This was characterized by significantly elevated pro-inflammatory cytokines such as G-CSF, TNF-α, IL-1α, IL-1β, and IL-6, excessive neutrophil infiltration, and reduced pulmonary lymphocyte levels as tuberculosis (TB) progressed." (PMID 39178329, 2024). "Immunopathology of human tuberculosis (TB) in a subgroup of patients is characterized by aberrantly high concentrations of inflammatory cytokines, for example Interleukin (IL)-6." (PMID 39511560, 2024). "Therefore, a decrease in IL-6 plasma concentrations under treatment may also indicate recovery from immunopathology during active tuberculosis." (PMID 35759173, 2023).
tuberculosis (continued). "Importantly, majority of deaths in our study occurred during tuberculosis treatment and, the association between IL-6 and mortality was independent of baseline disease severity and duration of symptomatic illness prior to testing." (PMID 34711538, 2022). "Hence there was no indication for an association between IL-6 plasma concentrations and impaired IL-7 T-cell response of tuberculosis patients." (PMID 28582466, 2017). "Another study also reported increased IL-6 in subjects with active TB disease compared to those with latent tuberculosis infection." (PMID 26359865, 2015). "Furthermore, in in vivo studies in IL-6-deficient mice, no repression in Cyp3a11 was seen on treatment with turpentine or tuberculosis vaccine." (PMID 18059400, 2008). "BACKGROUND: This study explores correlations between serum IL-6 levels, lipid metabolism, and nutritional status in pulmonary tuberculosis patients to advocate for integrating metabolic-nutritional assessments into routine TB care." (PMID 41680666, 2026). "Conversely, TB, caused by M. tuberculosis, elicits a strong immune response marked by the activation of immune cells and increased production of pro-inflammatory cytokines such as TNF-α, IL-1β, and IL-6." (PMID 40917351, 2025). "Previous studies have revealed that, IL-6 and TNF play crucial role in the immune response to tuberculosis." (PMID 39015338, 2024). "In an anti-tuberculosis drug-induced liver injury rat model, pyrrolidine dithiocarbamate effectively decreased the serum level of cytokines (TNF-α, IL-1β, and IL-6) by repressing the phosphorylation of JAK2 and STAT3." (PMID 38543164, 2024). "Recent evidence suggests that IL-6, IL-8, and TNF-α are not only protective in tuberculosis but that the picture is more complex." (PMID 38933114, 2024). "Both of these processes overlap at the systemic (the general symptoms of tuberculosis and thyrotoxicosis are similar) as well as local level, i.e., in the thyroid gland itself as atrophic inflammation (TNF alpha, IL-1, IL-6) with apoptosis and destruction." (PMID 39767631, 2024). "Notably, IL-6/IL-10 ratios showed strongest capacity to discriminate TB-Sp and TB-Pb (AUC: 0.88, p < 0.0001), suggesting that opposing IL-6 and IL-10 levels characterize these tuberculosis patient subgroups." (PMID 35759173, 2023). "Six cytokines, i.e., IL-6, IP-10, IL-10, IL-22, IFN-γ, and GM-CSF, were significantly higher in plasma samples from patients with tuberculosis." (PMID 35759173, 2023). "IL6, IL10, pSTAT3, and SOCS3 have been identified as influential factors distinguishing tuberculosis patients from healthy individuals." (PMID 37834286, 2023). "Serum IL-6 elevation was found in PTB patients, and the level of serum IL-6 was consistent with the progression or healing of tuberculosis." (PMID 37077246, 2023). "In a recent report, the genes coding for IL-1β, TNF, IL-6, and JAK2 accounted for four of the seven most influential hub genes in the host response to tuberculosis disease." (PMID 36059986, 2022). "Similar to tuberculosis with HIV superinfection in mice, we observed increased levels of IL-10 and IL-6 in superinfected tissues compared to those in both the SARS-CoV-2-alone and tuberculosis-alone groups." (PMID 36200898, 2022). "The study claimed that the ability of the plant extracts to increase the IFN-γ, IL-6, and TNF-α production by leukocytes enabled eradication of mycobacteria in tuberculosis (TB) by inducing the release of NO." (PMID 31440162, 2019). "The effects of interleukin gene (IL4, IL6, IL10) on tuberculosis were assessed by logistic regression analysis under three genetic models, including dominant, recessive and log-additive models." (PMID 29662655, 2018). "Percentages of IL-6+ and TNF-α+ neutrophils were lower in HIV-tuberculosis patients (q = 0.01 and q = 0.07, respectively), whereas concentrations of CSF-3, IFN-ɣ, and IL-1RA were higher." (PMID 28369200, 2017).